BRAF (B-Raf proto-oncogene, serine/threonine kinase)
Diseases named in the same sentence as BRAF in open-access papers (continued):
Sharing a sentence is not in itself a finding about the gene and the disease.
melanoma (continued). "Since the identification of activating mutations of BRAF in melanoma, the technology for detection has improved dramatically." (PMID 22175026, 2011). "Mutations leading to the activation of BRAF (the B isoform of RAF) were detected in 27-70% of melanoma, 36-53% of papillary thyroid cancer, 5-22% of colorectal cancer, and 30% of ovarian cancer." (PMID 22087839, 2011). "We also found that the combination was effective in melanoma cells carrying either BRAF or NRAS activating mutations, since A375, 1205Lu, and WM239a lines each have BRAFV600 mutations, while WM852c and SBCL2 lines have NRASQ61 mutations." (PMID 21897876, 2011). "Another MEK1/2 inhibitor, GSK1120212, is in Phase II for BRAF-mutant melanoma as well as for melanomas with GNAQ and GNA11 mutations." (PMID 21479172, 2011). "Activating BRAF mutations are present in approximately 70% of cutaneous malignant melanomas and 82% of melanocytic naevi." (PMID 21827678, 2011). "BRAF somatic missense mutations are reported in 66% of malignant melanomas and at a lower frequency in a wide range of other human cancers." (PMID 22174938, 2011). "In the melanoma group, we compared patients with V600K BRAF mutations vs. non-V600K BRAF mutations (the vast majority being V600E)." (PMID 22039425, 2011). "While in the second phase I study, only one response was seen in fourteen patients with melanoma, though this subject had a documented BRAF mutation and a complete response ongoing for over two years at the time of publication." (PMID 22175026, 2011). "The frequency of BRAF mutation in primary melanomas ranges from 36 to 45% and 42–55% in metastatic melanoma." (PMID 21139585, 2011). "One key discovery of the last decade is the identification of activating mutations in the serine/threonine kinase BRAF in up to 50% of all melanomas." (PMID 21505227, 2011). "With the discovery of an activating mutation of BRAF in 50–60% of all melanoma, with 90% of these tumors carrying a substitution at V600, a first tumor-specific target for a treatment was identified in 2002." (PMID 22007305, 2011). "The particular importance of this action is suggested by an intriguing parallel recently discovered between HCL and melanoma: they both carry a mutation in the BRAF gene." (PMID 24213115, 2011). "Multivariate analysis by logistic regression model showing the clinico-pathological features correlated with the BRAF mutation in melanoma patients." (PMID 22039425, 2011). "BRAF encodes a serine/threonine-protein kinase and is the most commonly mutated gene in melanoma (observed to be mutated in 40–70% of melanoma)." (PMID 21479172, 2011). "Since fistulae experience persistent inflammation, the fact that this melanoma harbours a BRAF mutation strengthens the view that oxidative stress caused by inflammatory processes plays an important role in the genesis of BRAF gene mutations." (PMID 21827678, 2011). "The finding of the selection of mutant BRAF alleles in melanoma progression appears to be significant in view of the recent development of selective BRAFV600E kinase inhibitors that showed successful preliminary clinical results." (PMID 21224857, 2011). "We further investigated the behavior of mutBRAF melanoma with V600K substitution compared to other subtypes of BRAF mutation." (PMID 22039425, 2011). "We tested a combination of vemurafenib and metformin in a panel of melanoma cell lines with defined BRAF and NRAS mutations." (PMID 21609436, 2011). "DNA obtained from melanoma tissue was analysed by automated direct sequencing and the V600E (T1799A) mutation was detected in exon 15 of the BRAF gene." (PMID 21827678, 2011). "Subtype 1.4 is associated with aberrations in both the MAPK and CDK pathways, specifically activation of BRAF and over-expression of CCND1/Cyclin D. The CDK pathway has been suggested to contribute to metastasis of melanoma with BRAF mutations." (PMID 21479172, 2011).
melanoma (continued). "The discovery of activating BRAF V600E mutations in 50% of all melanoma patients and the development of small molecule BRAF inhibitors looks set to revolutionize the therapy of disseminated melanoma." (PMID 21505227, 2011). "Single-cell mutation analyses revealed that four of five primary melanomas contained both BRAF-wild-type and BRAF-mutant tumour cells." (PMID 21224857, 2011). "In that mouse model, LKB1 is one of the major downstream targets and uncoupling of the LKB1-AMPK pathway by oncogenic BRAF is one possible mechanism to promote the proliferation of melanoma cells with BRAF mutations." (PMID 21911917, 2011). "For instance, patients with colorectal cancer and BRAF mutation showed a trend towards poor overall survival from diagnosis while, in patients with melanoma, the presence of a BRAF mutation was associated with a trend towards better survival." (PMID 22039425, 2011). "Since the discovery of frequent activating BRAF mutations in melanoma, myriads of papers have published reporting the detection of BRAF mutations in melanoma." (PMID 21224857, 2011). "In the phase I clinical trial, vemurafenib led to significant levels of tumor shrinkage in 80% of patients whose melanomas harbored the BRAF V600E mutation." (PMID 21505227, 2011). "Recent clinical studies have demonstrated that the presence of a BRAF mutation is prognostic for melanoma and is associated with reduced survival in the metastatic setting." (PMID 21505227, 2011). "Two primary melanomas (cases 12 and 13) had minor BRAF mutant alleles other than V600E, such as K601E and V600K." (PMID 21224857, 2011). "BRAF is activated in approximately 7% all cancers, highest in melanoma, often activated by point mutations." (PMID 21422497, 2011). "A substitution of glutamic acid for valine at codon 600 (V600E) is the most common BRAF mutation in melanoma, occurring in over 90% of BRAF-mutated cases." (PMID 21224857, 2011). "In tumor types with more than 10 patients tested, BRAF mutations were most frequent in melanoma, in 23 (44%) of 52 tested patients." (PMID 21829508, 2011). "The discovery of activating BRAF mutations in melanoma prompted a flurry of drug discovery activity and the development of small molecule BRAF inhibitors." (PMID 21505227, 2011). "In melanoma cells, mutation in BRAF constitutively activates BRAF signaling, which regulates Cks1/Skp2-mediated p27 degradation and controls G1 cell cycle event." (PMID 21386910, 2011). "A recent manuscript reported on the direct antitumor effects of modulating AMPK in two melanoma cell lines, one with a BRAF mutation and another with an NRAS mutation." (PMID 21609436, 2011). "In human melanoma development, benign nevi often harbor BRAF mutations (e.g., V600E), which convert it into an active oncogene." (PMID 20230482, 2010). "The MAPK pathway is one of the most frequently activated pathways in cancer, and in melanoma mutations in RAS or BRAF lead to its activation." (PMID 20230482, 2010). "NRAS mutations occur in approximately 15% of melanomas and are mutually exclusive with BRAF mutations." (PMID 20406486, 2010). "Sequencing efforts led by the Cancer Genome Project identified BRAF mutations in the majority of the melanoma cell lines and primary tumor specimens." (PMID 20230482, 2010). "Initially, we assessed changes in MITF expression in six human melanoma lines harboring oncogenic mutations in BRAF or NRAS, and in which ATF2 expression was effectively inhibited by corresponding shRNA (shATF2)." (PMID 21203491, 2010). "Activating mutations of the BRAF oncogene have been found in 50–60% of primary melanoma, metastatic melanoma tissues, and melanoma cell lines by us and other groups." (PMID 21206909, 2010). "They specifically target BRAF cancer carrying a mutation at V600E (designated V600E BRAF) that occurs in about 50%–60% of melanomas and about 6%–8% of all solid tumors, including colorectal, thyroid, and ovarian tumors." (PMID 24281076, 2010).
melanoma (continued). "Melanoma cell lines with different NRAS/BRAF mutational status were treated in vitro with a range of concentrations of PLX4032 for 5 days." (PMID 20406486, 2010). "Although melanocytic nevi are benign lesions that rarely progress to malignant melanoma, they are altered in relation to normal melanocytes and frequently exhibit the oncogenic activating BRAF mutation V600E." (PMID 20975957, 2010). "Concentrations of PLX4720 ⩾3 μM were required for apoptosis induction across a panel of three BRAF-mutated melanoma cell lines (WM35, WM164 and 1205Lu)." (PMID 20531415, 2010). "Due to the ability of Hsp90 inhibitors to target several oncogenic proteins, melanomas with activating BRAF mutations, as well as those with WT BRAF activated by NRAS alike are sensitive to inhibitors like 17AAG." (PMID 21301046, 2010). "Through an initial series of experiments, we confirmed that PLX4720 had good selectivity for BRAF-mutated melanoma cell lines over those harbouring NRAS mutations and also demonstrated that PLX4720 was able to induce significant levels of apoptosis." (PMID 20531415, 2010). "Our data are consistent with the previous findings that Lkb1 loss prevents culture-induced cellular senescence, allows BRAF mutant melanoma cells to proliferate, and cooperates with activating Kras mutations in a mouse model of lung cancer." (PMID 20452353, 2010). "A large number of preclinical studies have now validated mutated BRAF as a bona fide therapeutic target in melanoma." (PMID 20531415, 2010). "Seventy-one tumors were successfully assayed for common mutations activating the MAPK pathway in melanoma, i.e., BRAF exon 15 and NRAS exon 2 mutations." (PMID 20140953, 2010). "Activating mutations of the BRAF gene have been found in ~70% of melanomas, in particular, the BRAF V600E mutation, which is also found in nevi that are thought to be pre-malignant lesions." (PMID 24619402, 2010). "PLX4032 has been recently evaluated in a phase I clinical trial of melanoma patients harbouring the BRAF-V600E mutation." (PMID 20531415, 2010). "It was noted that PLX4720 also reduced pRB protein phosphorylation, increased p27 expression, suppressed cyclin D1 expression and induced cleavage of PARP only in melanoma cell lines harbouring the BRAF-V600E mutation." (PMID 20531415, 2010). "Activating mutations of the NRAS and BRAF genes occur in ∼20 and 50% of malignant melanomas respectively, and are almost always mutually exclusive." (PMID 20140953, 2010). "A genetic hallmark of human melanoma is mutually exclusive mutations of BRAF and NRAS, which are found in more than 90% of tumors." (PMID 20701798, 2010). "As a consequence, RAS is mutated in melanoma, the cells (B16-F10) switch their signaling from BRAF to CRAF, then IGFBP7 expression is decreased, enabling the cells to escape from senescence and resulting in uncontrolled proliferation." (PMID 20158915, 2010). "The effect of PLX4032 was tested on melanoma cells isolated from primary and metastatic lesions in which BRAF, NRAS and PTEN mutations were characterized." (PMID 20149136, 2010). "The BRAF V600E mutation has been detected in a wide range of human cancers, including melanomas, thyroid carcinomas, sporadic CRC (10%) and others." (PMID 20485284, 2010). "For example, BRAF is mutated in many cancers, including malignant melanoma (27–70%), papillary thyroid cancer (36–53%), ovarian cancer (about 30%), and colorectal cancer (5–22%)." (PMID 21124782, 2010). "The most frequent mutation in the MAPK pathway is in the BRAF gene, present in 60-70% of malignant melanomas." (PMID 20406486, 2010). "BRAF mutation correlates with distinct histopathologic features, such as intraepidermal melanoma nest formation and a larger rounder border of the tumor with surrounding skin, suggesting surrogate markers can be used to select cases for molecular testing." (PMID 19949544, 2009).
melanoma (continued). "Although BRAF is also mutated in up to 80% of benign melanocytic naevi, the proportion of naevi harbouring a BRAF mutation that progress to melanoma is small, underscoring that further genetic events are required for the development of melanoma." (PMID 19724275, 2009). "80% of BRAF-mutated melanomas were found to contain a V600E substitution, which is thought to constitutively activate the kinase by mimicking phosphorylation." (PMID 19285540, 2009). "To confirm that, we performed an immunoprecipitation of the endogenous LKB1 in the BRAF mutant melanoma cells and examined the AMPKα association under low energy conditions with or without U0126 inhibitor." (PMID 19274086, 2009). "A majority of human melanomas have constitutively active MAPK/extracellular signal-regulated kinase (ERK) due to BRAF or N-Ras mutations." (PMID 19919690, 2009). "Activating mutations of BRAF have been found in colorectal, ovarian, thyroid, and lung cancers as well as in cholangiocarcinoma, but the highest rate of BRAF mutations (overall, about half of cases) have been observed in melanoma." (PMID 19828018, 2009). "Activating BRAF mutations have been detected in melanoma patients only at the somatic level and in common cutaneous nevi." (PMID 19828018, 2009). "NFAT transcriptional activity was increased in BRAF-mutated melanoma cells compared with wild-type cells." (PMID 19724275, 2009). "30-70% of melanomas show BRAF point mutations which alter the autoregulatory activation of the kinase, of which the V600E mutation is by far the most common." (PMID 19949544, 2009). "This study has demonstrated the detection of BRAF mutations in cfDNA extracted from the serum of patients with advanced melanoma enrolled in a phase II study of AZD6244 versus temozolomide." (PMID 19861964, 2009). "Although α6β4 integrin signals stimulate NFAT activity in breast cancer, we now identify that NFAT is activated by oncogenic BRAF signalling, which is the most frequently mutated gene in melanoma and a gene frequently mutated in many other cancers." (PMID 19724275, 2009). "The BRAFV600E activating mutation accounts for approximately 90% of BRAF mutations in melanoma and BRAFV600E drives melanomagenesis in mice." (PMID 19724275, 2009). "NRAS mutations are rarely found in benign acquired nevi (although seen in congenital nevi), arise later in melanoma development, and can produce melanoma in certain animal models and are thus are more clearly implicated in oncogenesis than BRAF mutations." (PMID 19949544, 2009). "Bcl-2 downregulation in melanoma cells after sorafenib treatment occurs in cell lines harbouring BRAF mutation but seems to be ERK-independent." (PMID 19878585, 2009). "Considering that 70% of human melanomas harbor BRAF activating mutations, we determined the phosphorylation status of LKB1Ser428 in different human melanoma cell lines harboring BRAFV600E activating mutations in serum free and complete medium conditions." (PMID 19274086, 2009). "Activating BRAF V600E mutations are also known to occur in subsets of thyroid and colon carcinomas, and similar to melanoma, the presence of the mutation also predicts for sensitivity to MEK inhibition." (PMID 19156138, 2009). "UACC903 and A375 melanoma cells showed an increase in the number of AMPKα molecules associated to LKB1 when BRAF signaling pathway was blocked." (PMID 19274086, 2009). "We next assessed the effect of overexpression of BRAFWT or the most common BRAF mutation in melanoma, BRAFV600E, on NFAT transcriptional activity in CHL-1 cells." (PMID 19724275, 2009). "NRAS mutations are also common in melanoma occurring in up to 30% of cases, and as the occurrence of NRAS or BRAF mutation in melanoma is mutually exclusive, up to 90% of melanomas harbour a mutated, hyperactive Ras–RAF signalling pathway." (PMID 19724275, 2009).
melanoma (continued). "Perhaps the greatest recent advance in understanding risk factors predisposing to melanoma has been the discovery of activating mutations in the BRAF gene, occurring in 50–70% of all melanomas." (PMID 19724275, 2009). "Hypoxia independent expression of HIF-1α is thought to be regulated by growth signaling pathways and the majority of melanomas have constitutively active ERK1/2 MAPK pathway due to BRAF or N-Ras mutations." (PMID 19919690, 2009). "While PIK3CA mutations are more prevalent in colon and breast cancer, BRAF mutation occurs at a high frequency in melanoma." (PMID 19492075, 2009). "PTEN is regulated as a tumor suppressor with complete PTEN loss (usually accompanied by genomic deletion) seen in 20-25% of melanomas (including those with BRAF mutation), and is highly associated with uniform high-level AKT activation." (PMID 19949544, 2009). "The majority of melanomas have constitutively active ERK1/2 MAPK pathway due to BRAF or N-Ras mutations." (PMID 19919690, 2009). "Considering the immunocytochemical results, all melanoma cell lines (7/7; 100%) with concurrent mutation of BRAF-NRAS and down-regulation of p16CDKN2A presented high expression levels of the activated pERK1-2 protein." (PMID 19799798, 2009). "BRAF mutations were identified in 66% of melanomas, and in smaller percentage in other human cancers including colorectal." (PMID 18577988, 2008). "We show that BRAF depletion caused a substantial decrease in the activity of the MITF promoter in melanoma cells." (PMID 18628967, 2008). "For example, the somatic mutation V599E in BRAF, commonly observed in melanoma, is known to activate the MEK-ERK cascade constitutively." (PMID 19517027, 2008). "Loss of function of the tumour suppressor PTEN, which results in activation of the PI3K/AKT pathway, occurs in 10–30% of melanomas, frequently concurrent with activating BRAF mutations." (PMID 18813315, 2008). "We have previously shown that because ERK is hyper-activated in melanoma cells in which BRAF is mutated, the MITF protein is constitutively down-regulated." (PMID 18628967, 2008). "Activating mutations of the protooncogene BRAF have been observed in approximately fifty percent of malignant melanomas." (PMID 18631381, 2008). "Previous research has also shown that the BRAF mutation frequency is lower in melanoma arising in sites protected from sun exposure compared with those from sun-exposed sites." (PMID 18985043, 2008). "In melanoma, these BRAF mutations are found in two small regions of the kinase domain of the BRAF molecule." (PMID 18985043, 2008). "It is interesting to note that one of our patients with a BRAF mutation suffered from melanoma located in an UV-exposed area of the conjunctiva." (PMID 19018266, 2008). "Using the more sensitive nested PCR approach we have identified the T1799A BRAF mutation in 4 of 20 (20%) ciliary body melanomas and 11 of 30 (40%) choroidal melanomas." (PMID 18985043, 2008). "Another strategy appears to be gene amplification, since the MITF gene is amplified in approximately 15% of melanoma cases in which BRAF is mutated." (PMID 18628967, 2008). "Somatic mutations in BRAF have been reported at a high frequency in numerous cancers including melanoma, thyroid, colorectal and ovarian." (PMID 18060073, 2007). "The most prevalent oncogenic BRAF mutation is the V600E BRAF mutation (previous terminology, V599E), which is present in 63% of melanomas." (PMID 16880785, 2006). "Reports of activating BRAF mutations in most melanomas and around 80% of naevi provided a likely candidate for the mutation that most commonly initiates proliferation." (PMID 16880792, 2006).